TSPAN16 (tetraspanin 16)
Synonyms: TM4SF16; TM4-B; TM-8
Tractability: Antibody: UniProt predicts a signal peptide or a membrane-spanning region; its Gene Ontology location is reachable by antibodies, with medium confidence; the Human Protein Atlas places it where antibodies can reach.
Gene: Protein-coding gene on chromosome 19 (11,296,139 to 11,326,996, forward strand). Ensembl gene ENSG00000130167.
Subcellular location: Membrane
Subcellular location (Human Protein Atlas): Plasma membrane
Gene Ontology:
Molecular function: protein binding
Cellular component: membrane; plasma membrane
Genetic constraint (gnomAD): Loss-of-function variants: 21 observed, 25.68 expected, observed/expected ratio (o/e) 0.82, 90% interval 0.58 to 1.18. The upper end of that interval is the gene's LOEUF score, 1.18, which puts it in group 5 of 6, group 1 being the genes least tolerant of losing a copy. Missense variants: 268 observed, 306.89 expected, observed/expected ratio (o/e) 0.87, 90% interval 0.79 to 0.97. Synonymous variants: 121 observed, 127.05 expected, observed/expected ratio (o/e) 0.95, 90% interval 0.82 to 1.11.
Homologues: Orthologues: chimpanzee TSPAN16 (93% identical), macaque TSPAN16 (79% identical), rabbit TSPAN16 (68% identical), guinea pig TSPAN16 (56% identical). Paralogues in human: TSPAN1 (23% identical), TSPAN18 (22% identical), TSPAN5 (22% identical), CD82 (21% identical), TSPAN14 (21% identical), TSPAN17 (21% identical), TSPAN33 (21% identical), CD151 (20% identical), TSPAN10 (20% identical), TSPAN11 (20% identical), TSPAN6 (20% identical), TSPAN19 (19% identical), and 20 more.
Diseases named in the same sentence as TSPAN16 in open-access papers:
TSPAN16 is named in the same sentence as 3 diseases in open-access papers, as found by Europe PMC text mining. Sharing a sentence is not in itself a finding about the gene and the disease. The quoted sentences say what the papers report.
atherosclerosis (1 paper, 2011). A disease characterized by the build-up of fatty material and calcium deposition in the arterial wall resulting in partial or complete occlusion of the arterial lumen. "The last two terms, based on AF289562 (AF2) and TSPAN16 are genes of unknown function that will require further work to clarify their role in atherosclerosis." (PMID 21443790, 2011).
cancer (1 paper, 2025). A tumor composed of atypical neoplastic, often pleomorphic cells that invade other tissues. "Research indicates that TSPAN16 is characteristically expressed at reduced levels in 33 varieties of cancer when contrasted with their corresponding normal tissue samples, which aligns with our findings." (PMID 41347075, 2025). "Our study identified TSPAN16 as being regulated by hsa-miR-200b-3p, a microRNA with well-documented roles in cancer initiation and progression." (PMID 41347075, 2025). "To date, the exploration of TSPAN16 in the context of cancer remains scarce." (PMID 41347075, 2025).
TSPAN16 also shares sentences with these, for which no sentence is quoted: tumor (1 paper).